AKR1B1 (aldo-keto reductase family 1 member B)
Diseases named in the same sentence as AKR1B1 in open-access papers (continued):
Sharing a sentence is not in itself a finding about the gene and the disease.
tumor (continued). "Additionally, AKR1B1-mediated endogenous fructose metabolism regulates proliferation and ameboid migration through the cyclin and RhoA-ROCK2 signaling pathways, ultimately increasing tumor malignancy." (PMID 39406918, 2024). "Notably, AKR1B1, CD36, ABCA1, PRKD1, OSBPL1A, and FABP3 showed varied expressions in specific cells, suggesting their significant roles in STAD carcinogenesis, further confirmed by elevated mRNA levels in tumor tissues via qRT-PCR." (PMID 38440405, 2024). "Meanwhile, AKR1B1 inhibition could block the mTOR pathway activation by activating 5′ adenosine monophosphate-activated protein kinase (AMPK) as it inhibits the phosphorylation of mTOR, Raptor, eIF4E, S6K, and 4E-BP1, thus inhibiting tumor growth." (PMID 37751590, 2023). "Additionally, the knockdown of AKR1B1 expression level in GC cell lines could effectively suppress the AKT-mTOR pathway and inhibit the proliferation and migration of tumor cells." (PMID 37751590, 2023). "Alternatively, AKR1B1 inhibition could prevent activation of the mTOR pathway through 5' adenosine monophosphate‐activated protein kinase (AMPK) activation as it prevents phosphorylation of mTOR, Raptor, eIF4E, S6K and 4E‐BP1, thereby inhibiting tumour growth." (PMID 32633024, 2020). "Despite the fact that there is still no clear correlation between the expression of AKR1B1 and tumour creation in CRC tissues, several evidence suggest that AKR1B1 could play a role in the tumorigenesis of CRC." (PMID 32633024, 2020). "Aldo-keto reductase 1 member B1 (AKR1B1) that drives glucose flux through the polyol pathway, is also highly expressed in ACC and may play a critical role in tumor development and progression through carbonyl detoxification, retinoic acid homeostatic regulation, and lipid metabolic control." (PMID 25691058, 2015). "Additionally, the study did not consider other potential functions of AKR1B1 beyond fructose metabolism, which could impact the metabolic phenotype of tumor cells." (PMID 39406918, 2024). "AKR1B1 may promote tumor metastasis via nonpolyol pathways such as NF-κB and PGF2A." (PMID 38200154, 2024). "More importantly, knockdown of ZNF521 failed to inhibit GC progression in the presence of AKR1B1 overexpression, demonstrating that AKR1B1 is essential in the ZNF521‐mediated tumor‐promoting activity of ZNF521." (PMID 36397644, 2023). "No significant changes in expression of AKR1B1, AKR1D1, AKR7A2, CBR1, CYP2C8, and CYP2C9 between tumor and control tissues were found." (PMID 25526449, 2014).
retinopathy (26 papers, 2008 to 2025). "AKR1B1, an NADPH-dependent aldo-keto reductase, is involved in diabetic cataracts and retinopathy." (PMID 35860180, 2022).
metabolic disease (10 papers, 2013 to 2026). A congenital disorder (due to inherited enzyme abnormality) or acquired (due to failure of a metabolically important organ) disorder resulting from an abnormal metabolic process. "This positions AKR1B1 as a promising therapeutic target for diseases in which EMT acts as a pathological driver, with broad implications for oncology, fibrotic disorders, and metabolic disease complications." (PMID 41154825, 2025).
liver (2 papers, 2015 to 2023). "Indeed, not only colorectal, but also liver, stomach, and pancreas tumors present high rates of hypermethylation of PTGIS, AKR1B1, PTGER3, and PTGFR." (PMID 26207152, 2015).
endocrine disorders (1 paper, 2022). "The results showed that low temperature induces endocrine disorders, affects basal metabolism and glucose metabolism, inhibits antioxidant enzyme activity (GST) and immune gene expression (AKP, CAT, GGT, and AKR1B1), and slows individual growth." (PMID 36139854, 2022).
inflammatory myopathy (1 paper, 2018). "Confirming our earlier descriptive myopathological results on SLC5A3, SLC6A6, and AKR1B1 expression, we found these factors upregulated in regenerating muscle fibers present in biopsies in this new cohort of inflammatory myopathy patients." (PMID 30364257, 2018).
AKR1B1 also shares sentences with these, for which no sentence is quoted: type 1 diabetes (10 papers); atherosclerosis (9); liver cancer (6); galactosemia (5); cardiovascular disorder (3); fatty liver disease (3); heart failure (3); hyperlipidemia (3); acute myelogenous leukemia (2); chronic kidney disease (2); dyslipidemia (2); endothelial dysfunction (2); ischemia (2); Neurological Disease (2); non‐alcoholic fatty liver diseases (2); peripheral neuropathy (2); Stroke (2); systemic inflammatory response syndrome (2); Abdominal obesity (1); acute leukemia (1); adenocarcinoma (1); adrenal tumors (1); adrenocortical tumors (1); alcoholic hepatitis (1); allergic asthma (1); allergic rhinitis (1); alopecia areata (1); Alzheimer disease (1); amyotrophic lateral sclerosis (1); behavioral disorders (1).
A further 61 diseases each share a sentence with AKR1B1 in 1 paper.